BDNF (brain derived neurotrophic factor)
Diseases named in the same sentence as BDNF in open-access papers (continued):
Sharing a sentence is not in itself a finding about the gene and the disease.
epilepsy (continued). "In the human neocortex of epilepsy patients, a specific ERK activation pattern was linked to CREB phosphorylation and followed by enhanced transcription of CREB targets such as BDNF." (PMID 27855659, 2016). "Using the KA-induced epilepsy paradigm, many studies have demonstrated that brain-derived neurotrophic factor(BDNF) and its receptor tropomyosin-related kinase B(TrkB) play critical roles in seizures and epileptogenesis." (PMID 27273072, 2016). "Several studies have shown that manipulations that perturb BDNF-TrkB signaling reduce the development of epilepsy." (PMID 27721996, 2016). "In the current study, the abnormally high level of BDNF in epilepsy patients and the negative regulation of miR-155 on BDNF were verified." (PMID 27303295, 2016). "Evidences demonstrate that epilepsy influences the expression of BDNF both at mRNA and BDNF protein levels probably due to modulation of excitatory and inhibitory neurotransmission." (PMID 24605339, 2014). "Continuous intrahippocampal administration of BDNF likely attenuated the development of epilepsy mainly through increased expression of neuropeptide Y (NPY)." (PMID 24287913, 2013). "Most of the evidences linking BDNF to epilepsy are based on the fact that BDNF is markedly upregulated by seizure activity, especially in the dentate gyrus and CA1–CA3 pyramidal cell layers." (PMID 23840662, 2013). "Seizures can rapidly elevate both glutamate and BDNF levels in adult and immature animal models of epilepsy, which is in agreement with our findings." (PMID 22567115, 2012). "Nevertheless, the role of BDNF on epilepsy is controversial, because both antiepileptic and pro-epileptic effects have been reported." (PMID 23118939, 2012). "In developing neurons and epilepsy, BDNF is the endogenous signal that induces EGR3 expression via a PKC/MAPK-dependent pathway, and then EGR3 up-regulates the expression of GABRA4 by binding its promoter." (PMID 20156358, 2010). "Furthermore, our results demonstrate that induction of epilepsy enhanced the level of BDNF systemically in blood and locally within brain tissues." (PMID 40177581, 2025). "In epilepsy, BDNF exhibits dual roles, exerting both antiepileptic and pro-epileptic effects." (PMID 41020886, 2025). "The effect of seizures and epilepsy on BDNF remain controversial." (PMID 40291844, 2025). "Here, results supported the hypothesis of targeting the BDNF-TrkB axis in the prevention of epilepsy." (PMID 39776284, 2025). "For instance, BDNF up-regulation in chronic epilepsy models exhibits dualistic properties, potentially exacerbating hyperexcitability through TrkB receptor-mediated potentiation of glutamatergic synapses—a phenomenon not yet systematically evaluated in VD intervention studies." (PMID 40629476, 2025). "However, TrkB receptor agonists attenuate the development and progression of epilepsy through a BDNF-independent pathway." (PMID 40380033, 2025). "It is important to note that BDNF plays a complex and multifaceted role in epilepsy." (PMID 40177581, 2025). "Specifically, IDO activation may contribute to epilepsy progression, potentially through mechanisms involving the BDNF/TrkB signaling pathway, oxidative stress, and mitochondrial respiratory chain activity." (PMID 41020886, 2025). "In addition, BDNF-TrkB signaling mediates the increase in neuronal excitability coupled to the development of seizures in experimental models of epilepsy." (PMID 40890771, 2025).
epilepsy (continued). "Thus, the goal of the present review was to highlight the protective and detrimental roles of BDNF in epilepsy." (PMID 38006577, 2024). "BDNF may inhibit epilepsy by phosphorylating specific subunits of GABAergic neurones, thereby attenuating the decrease in GABAergic neuronal excitability associated with epilepsy." (PMID 38707431, 2024). "However, previous reports have also shown opposite results indicating that BDNF upregulates KCC2 in lesion models such as epilepsy, spinal cord injury, and axotomized corticospinal neurons." (PMID 39337430, 2024). "Furthermore, BDNF can reduce epileptogenesis-induced inflammation through the improvement of BBB integrity in rats with experimental epilepsy." (PMID 38006577, 2024). "Senescent‐like microglia in aged animals demonstrate elevated transcript levels for a range of SASPs, including IL‐10, IL1B, IL‐6, TNFA, and BDNF, all of which may contribute to epilepsy and seizure vulnerability." (PMID 39031751, 2024). "Thus, BDNF treatment significantly improved memory function in rats after pilocarpine-induced epilepsy." (PMID 39408863, 2024). "Epilepsy has been found to downregulate the level of BDNF in the hippocampus." (PMID 39650161, 2024). "In conclusion, there is a strong controversy concerning the potential role of BDNF in epilepsy." (PMID 38006577, 2024). "In this manner, BDNF mimetics could be effective in the management of epilepsy by reducing hippocampal neuronal injury." (PMID 38006577, 2024). "Therefore, the present review aims to revise the potential role of BDNF in epilepsy regarding its beneficial and detrimental roles." (PMID 38006577, 2024). "At the organism level, BDNF overexpression in cortical neurons of Sip1wt/fl mice promoted an increase in motor and exploratory activity of mice and resulted in 100% survival of these mice in the pilocarpine model of epilepsy." (PMID 39408863, 2024). "Excessive BDNF expression disrupts the regulation of cortical networks in epilepsy." (PMID 38707431, 2024). "Therefore, brain insults such as febrile seizure and encephalitis which induce the expression of BDNF trigger epileptogenesis by altering neuronal circuits in many brain areas, and can induce epilepsy." (PMID 38006577, 2024). "Given the long-postulated role of BDNF in epileptogenesis, TRPC3 channels may be a critical component underlying the pathophysiology of seizures and epilepsy." (PMID 39408863, 2024). "Furthermore, hesperidin protects from PTZ-induced neurotoxicity and epilepsy via stimulation of the cAMP response element binding protein (CREB)/BDNF pathway." (PMID 38006577, 2024). "Applying the Steiger test to the reverse analysis of nITH, epilepsy, and various subtypes of epilepsy indicated potential absence of the outcomes’ causal influence on plasma BDNF." (PMID 38707431, 2024). "We observed null causal relationships between plasma BDNF levels and the majority of disorders investigated, except for nITH, epilepsy, focal epilepsy, and non-lesional focal epilepsy." (PMID 38707431, 2024). "Quantitative estimation of mRNA levels in the hippocampus of patients with resistance epilepsy compared to autopsy controls showed increased mRNA hybridization of BDNF with significant reduction of mRNA hybridization of Ca+ 2/calmodulin-dependent protein kinase II." (PMID 38006577, 2024). "Despite of that the brain-derived neurotrophic factor (BDNF) is implicated in the pathogenesis of epileptogenesis and epilepsy, BDNF may have a neuroprotective effect against epilepsy." (PMID 38006577, 2024). "Higher expression of α-Syn in intractable epilepsy could explain the reduction of circulating BDNF in patients with severe and resistant epilepsy." (PMID 38006577, 2024). "Taken together, the potential role of BDNF in epilepsy could detrimental by interrupting the neuronal inhibitory/excitatory axis, or beneficial by inhibiting the excitability of hippocampal glutamatergic neurons." (PMID 38006577, 2024).
epilepsy (continued). "In sum, there is a strong controversy concerning whether BDNF serum levels in epilepsy could be protective or detrimental." (PMID 38006577, 2024). "Therefore, the assessment of BDNF levels in epilepsy should be related to other neuronal signaling pathways and types of epilepsy in both preclinical and clinical studies." (PMID 38006577, 2024). "It has been shown that expression of BDNF and TrkB was increased in mice with epilepsy." (PMID 38006577, 2024). "This foundation excited many researchers to illustrate the link between BDNF and epilepsy." (PMID 38006577, 2024). "Inhibition of machinery cleavage of pro-BDNF to BDNF and reduction of plasminogen proteolytic activity following seizure and SE could be a possible mechanism for decreasing BDNF in epilepsy." (PMID 38006577, 2024). "Thus, autophagy/BDNF pathway is an essential pathway to maintain neuronal integrity and attenuate epileptogenesis and the development of epilepsy." (PMID 38006577, 2024). "Therefore, the measurement of BDNF in epilepsy should be related to other neuronal signaling pathways and types of epilepsy in both preclinical and clinical studies." (PMID 38006577, 2024). "BDNF/TrkB axis is highly upregulated in the hippocampus in animal model epilepsy." (PMID 38006577, 2024). "However, compared with groups of healthy individuals, both increased and decreased BDNF levels were found in the blood of patients with epilepsy." (PMID 38203674, 2023). "Larger prospective clinical studies could be of interest, controlling for treatment, to further investigate the possible role of BDNF as a potential biomarker of epilepsy severity and psychiatric comorbidities." (PMID 37923391, 2023). "Extending these findings, a series of papers have been published in the last decade, indicating a strong negative association between serum BDNF level and epilepsy duration." (PMID 37539386, 2023). "However, the neurotrophic and neuroprotective properties of BDNF can be potentially used to treat epilepsy, e.g., by inhibiting BDNF-TrkB signaling and reinforcing the NPY system." (PMID 38069144, 2023). "Increasing BDNF seems promising in various diseases, but in epilepsy it may promote epileptogenesis." (PMID 36672199, 2023). "Extending this concept to epileptogenesis (the period between the initial insult and the occurrence of the first spontaneous seizures), it can be hypothesized that lower BDNF levels during epileptogenesis could predict epilepsy development." (PMID 37923391, 2023). "BDNF is well established to be involved in the pathogenesis of a multitude of neurological and psychiatric disorders, such as Parkinson’s and Alzheimer’s diseases, epilepsy, depression, anxiety disorders and many others." (PMID 37539386, 2023). "Abnormalities in conversion of pro-BDNF to BDNF have alreadybeen postulated as helping to explain certain neuropathological processesunderlying various brain disorders like bipolar depression or epilepsy." (PMID 35061219, 2022). "A membrane permeable peptide comprising the HIV-1 Tat domain and a TrkB sequence, able to block PLCγ1 binding to residue 816 of TrkB, has been shown to prevent epilepsy development following intra-amygdala KA while preserving the neuroprotective effects of BDNF." (PMID 36180719, 2022). "These variable results may due to multiple factors, including the diverse animal models of epilepsy, the period of BDNF therapy in the history of epilepsy, the method of delivery, and subcellular localization." (PMID 35557046, 2022). "Our previous studies have shown that BDNF is involved in comorbidities of epilepsy and migraine." (PMID 35382731, 2022). "These were consistent with the results of tests for epileptic and migraine‐like behaviors, which indicates that BDNF–TrkB signaling may also have antiepileptogenic and analgesic effects in epilepsy comorbid with migraine." (PMID 35557046, 2022). "Targeting the BDNF/TrkB pathway can also prevent or inhibit epilepsy." (PMID 36263167, 2022).
epilepsy (continued). "Because of the complexity of epilepsy–migraine comorbidity, it is still unclear whether and how the overexpression of BDNF in PAG region contributes to modulate the comorbidities behavior." (PMID 35557046, 2022). "The important finding is that BDNF overexpression in the vlPAG region highly significantly decreases the frequency and duration of spontaneous seizures as well as pain sensitivity in the epilepsy–migraine comorbid rat." (PMID 35557046, 2022). "This is of interest because BDNF is a potent modulator of epileptogenesis; BDNF expression reportedly increased in the brains of epileptic patients and animal models of epilepsy, whereas disruption of BDNF/TrkB signaling suppressed seizure activity in epileptic mouse models." (PMID 36605420, 2022). "Some studies suggest that BDNF may facilitate or inhibit the process of epilepsy formation, but its exact role and potential mechanisms remain unclear." (PMID 35431921, 2022). "BDNF is a target of miR-134, which is decreased in epilepsy and they further found that miR-134 oligonucleotide could increase the expression of BDNF and reduce the frequency and duration of seizure in animal models." (PMID 35119588, 2022). "In the two epilepsy models above, the increases in c-fos, c-jun, and brain-derived neurotrophic factor (BDNF) expression were attributed to the decreased expression of class I HDACs, the increased phosphorylation of histone H3, and the excessive acetylation of histone H4 in rat hippocampal neurons." (PMID 36672596, 2022). "Our research aimed to investigate whether microglia and their interactions with neurons via the FKN/CX3CR1 axis in the thalamic cortical network are involved in the comorbidities of epilepsy and migraine by regulating the expression of BDNF." (PMID 35382731, 2022). "In conclusion, the present work suggests that increased release of BDNF could contribute to the development seizures and epilepsy induced by TMEV infection." (PMID 35874836, 2022). "Studies have shown that BDNF levels in AD patients decreased to a certain extent, whereas increasing the serum expression of BDNF prevented the occurrence of epilepsy and AD and acute application of exogenous BDNF increased neuronal activity and synaptic transmission in cultured neurons." (PMID 36406589, 2022). "In recent years, BDNF has also been found to play a role in formation of epilepsy." (PMID 35431921, 2022). "It is hypothesized that BDNF may inhibit epilepsy by promoting phosphorylation of certain subunits of GABAergic neurons to attenuate the disease-induced decrease in GABAergic neuronal excitability." (PMID 34899313, 2021). "The close relationship among miRNAs, the BDNF-TrkB pathway, and epilepsy suggests that miRNAs acting on the BDNF-TrkB pathway may be a promising antiepileptic treatment strategy." (PMID 34899313, 2021). "In general, many cellular and animal studies have shown a consistent relationship between decreased levels of BDNF and increased incidence of epilepsy, or that recovery of BDNF expression may alleviate epilepsy in experimental epilepsy." (PMID 34899313, 2021). "Additionally, BDNF plays a key role in epilepsy pathology in that it is substantially downregulated in epilepsy models." (PMID 33815100, 2021). "Furthermore, many proteins and molecules within the BDNF-related signaling pathway are expected to be molecular targets for clinical epilepsy detection and treatment, which may be exploited to participate in the clinical treatment, risk assessment and prognosis of epilepsy." (PMID 34899313, 2021). "Overall, BDNF may contribute to the development of epilepsy by activating its downstream pathways to modulate a variety of factors, (e.g., neuronal cell damage and apoptosis, mossy fiber sprouting, increase in ROS, etc.)." (PMID 34899313, 2021). "The other hypothesis suggests that abnormal activity or increased levels of BDNF play a positive role in inducing epilepsy and promoting epileptogenesis." (PMID 34899313, 2021).
epilepsy (continued). "Therefore, reductions in BDNF levels should be carefully considered when treating epilepsy patients." (PMID 35194435, 2021). "On the other hand, epileptogenic models in which BDNF signaling has been tested are mostly based on epilepsies of structural origin, and whether these signaling pathways are shared in different etiologies remains a matter of debate." (PMID 34681281, 2021). "BDNF is one of the most studied molecules in the pathophysiology of epilepsy." (PMID 33825777, 2021). "In recent years, the miRNAs that may be involved in BDNF-mediated epilepsy have received increasing attention." (PMID 33776649, 2021). "The physiological role of BDNF in epilepsy has been well documented, but it is still unclear whether the effect of BDNF is facilitating or inhibiting epileptic seizures." (PMID 33808762, 2021). "Brain-derived neurotrophic factor (BDNF), highly expressed in the brain, is a crucial regulator of neuron function, and the altered expression of BDNF is related to epilepsy, while GR shares several similarities with BDNF and is able to regulate BDNF expression level." (PMID 34697589, 2021). "Other clinical studies have found that several miRNAs are involved in the BDNF-TrkB pathway and certain miRNAs can increase the expression of BDNF and activate its downstream signaling pathways, which have an inhibitory effect on the development of epilepsy." (PMID 34899313, 2021). "In addition, BDNF and its conjugated receptor (TrkB) is increased in both animal models and human epilepsy patients, especially in the temporal and hippocampal regions which provides a surgical strategy for epilepsy surgery." (PMID 34899313, 2021). "Interestingly, seven-day chronic infusion of BDNF into the hippocampus resulted in attenuation of the development of kindling in a rat epilepsy model." (PMID 33825777, 2021). "In summary, these cellular and animal studies have shown that increased BDNF levels seem to be correlated with the incidence of epilepsy and increased BDNF may be companied with the neuronal cell damage." (PMID 34899313, 2021). "Only a few studies reported the relationship between serum levels of BDNF and epilepsy in patients." (PMID 34899313, 2021). "A clear determination of BDNF role in the kindling process is difficult because some studies that revealed its protective effect against processes of neuronal damage observed in the experimental models of epilepsy." (PMID 34333674, 2021). "It was also shown that stimulation of vagal nerve was efficient for treatment-resistant epilepsy and depressive patients with sustained effects over time by elevating brain-derived neurotrophic factor (BDNF) expression in the rat brain by phosphorylation of TrkB." (PMID 32322213, 2020). "In our study, BDNF was identified as the target gene of ADORA2A on epilepsy by PPI analysis." (PMID 33262686, 2020). "However, elevated expression of BDNF is known to be involved in the pathogenesis of epilepsy in various animal models and human brains." (PMID 33424762, 2020). "BDNF/TrkB signaling is thought to play a critical role in epilepsy." (PMID 33202963, 2020). "BDNF plays a key role in the survival of nerve cells and synaptic plasticity and has been involved in several neurological impairments such as Huntington, Alzheimer, and epilepsy." (PMID 32215171, 2020). "Moreover, the reduced activity of Kir4.1 channels elevates the levels of extracellular K+ and glutamate at tripartite synapses and facilitates astrocytic BDNF expression, which can promote the development of epilepsy." (PMID 33424762, 2020). "Thus, improved learning and memory in rats with epilepsy housed in an enriched environment with wheel running was accompanied by increased hippocampal neurogenesis and BDNF and VEGF transcripts." (PMID 33584215, 2020). "In addition, inhibition of BDNF/TrkB signaling has been shown to suppress the development of epilepsy in animal models." (PMID 33424762, 2020).